MIR548AX (microRNA 548ax)
Synonyms: hsa-mir-548ax
Gene: MicroRNA gene on chromosome X (11,318,614 to 11,318,686, reverse strand). Ensembl gene ENSG00000263652.
Homologues: Orthologues: chimpanzee MIR548AX (100% identical). Paralogues in human: MIR548H3 (88% identical), MIR548Z (86% identical), MIR548AN (84% identical), MIR548AH (82% identical), MIR548X2 (82% identical), MIR548AY (81% identical), MIR548AJ1 (79% identical), MIR548O2 (79% identical), MIR548AZ (78% identical), MIR548N (78% identical), MIR548AA1 (77% identical), MIR548F1 (77% identical), and 13 more.